LTO1 (LTO1 maturation factor of ABCE1)
Description:
The complex LTO1:YAE1 functions as a target specific adapter that probably recruits apo-ABCE1 to the cytosolic iron-sulfur protein assembly (CIA) complex machinery. May be required for biogenesis of the large ribosomal subunit and initiation of translation. May play a role in the regulation of proline metabolism and ROS production.
Synonyms: ORAOV1; TAOS1; CIAB1
Tractability: No criterion of Open Targets' tractability assessment is met for any kind of drug.
Gene: Protein-coding gene on chromosome 11 (69,653,076 to 69,675,416, reverse strand). Ensembl gene ENSG00000149716.
Subcellular location: Nucleus
Subcellular location (Human Protein Atlas): Nucleoplasm
Gene Ontology:
Molecular function: protein binding
Biological process: protein maturation; ribosomal large subunit biogenesis; translational initiation; telomere maintenance
Cellular component: nucleus
Genetic constraint (gnomAD): Loss-of-function variants: 1 observed, 1.15 expected, observed/expected ratio (o/e) 0.87, 90% interval 0.25 to 1.88. That is too few expected variants to judge how well the gene tolerates losing a copy. Missense variants: 24 observed, 20.39 expected, observed/expected ratio (o/e) 1.18, 90% interval 0.85 to 1.65. Synonymous variants: 7 observed, 5.98 expected, observed/expected ratio (o/e) 1.17, 90% interval 0.65 to 1.86.
Homologues: Orthologues: dog LTO1 (91% identical), guinea pig LTO1 (91% identical), pig LTO1 (91% identical), macaque LTO1 (88% identical), chimpanzee LTO1 (87% identical), rat Lto1 (78% identical), mouse LTO1 (77% identical), tropical clawed frog lto1 (53% identical).
Diseases named in the same sentence as LTO1 in open-access papers:
LTO1 is named in the same sentence as 22 diseases in open-access papers, as found by Europe PMC text mining. Sharing a sentence is not in itself a finding about the gene and the disease. The quoted sentences say what the papers report.
cancer (26 papers, 2010 to 2025). A tumor composed of atypical neoplastic, often pleomorphic cells that invade other tissues. "LTO1 is overexpressed in several cancer types and was found to prevent ROS-induced ribosomal damage." (PMID 37438342, 2023). "Since disregulation of LTO1 and MMS19 contribute to tumorigenesis, we inspected the catalogue of somatic mutations in cancer and identified alterations in 6 human genes that would lead to decreased TCR functionality." (PMID 37883440, 2023).
LTO1 also shares sentences with these, for which no sentence is quoted: tumor (11 papers); breast carcinoma (6); oral cancer (3); oral squamous cell carcinoma (3); head and neck squamous cell carcinoma (2); infection (2); squamous cell carcinoma (2); cervical cancer (1); colon cancer (1); esophageal squamous cell carcinoma (1); gastric cancer (1); gastrointestinal stromal tumor (1); laryngeal carcinoma (1); lung carcinoma (1); lymph node metastasis (1); metastatic tumor (1); non-small cell lung carcinoma (1); oesophageal cancer (1); sarcoma (1); tongue tumors (1); viral infection (1).